HIC1 (HIC ZBTB transcriptional repressor 1)
Diseases named in the same sentence as HIC1 in open-access papers (continued):
Sharing a sentence is not in itself a finding about the gene and the disease.
breast carcinoma (continued). "Therefore, restoration of HIC-1 function by demethylation may offer a therapeutic avenue in breast cancer." (PMID 22016618, 2011). "It was found that HIC1 expression was suppressed by HIC1 hyper-methylation in TNBC compared to normal breast cells and other breast cancer cells, which is consistent with previously reported results." (PMID 39339179, 2024). "IHC results in our clinical samples further confirmed the low protein level of HIC1 in breast cancer and LUAD, while the relatively high HIC1 protein expression in KIRC and SARC, which further validates HIC1 expression pattern in bioinformatics analysis." (PMID 37388742, 2023). "Immunohistochemistry (IHC) was employed to validate HIC1 expression in different cancers by our clinical cohorts, including lung cancer, sarcoma (SARC), breast cancer, and kidney renal clear cell carcinoma (KIRC)." (PMID 37388742, 2023). "A strongly positive expression of HIC1 was observed in SARC and KIRC, while low expression of HIC1 was detected in patients with LUAD and breast cancer." (PMID 37388742, 2023). "The expression of HIC1 was further verified by IHC across 4 different types of cancer by our cohorts, including LUAD, SARC, breast cancer, and KIRC." (PMID 37388742, 2023). "It was concluded that the HIC1 and RASSF1A hyper methylations can be used as prognostic markers of breast cancer in this population." (PMID 33883026, 2021). "Therefore, HIC1 may be a promising drug target for future breast cancer therapy." (PMID 31680974, 2019). "Hypermethylated in cancer 1 (HIC-1) is a tumor suppressor gene, which is epigenetically silenced in breast cancer." (PMID 25435951, 2015). "In the present study, we assessed HIC-1 as a candidate therapeutic target and observed altered cellular functions after the re-expression of HIC-1 in breast cancer cells." (PMID 24489730, 2014). "Accordingly, we detected high levels of CGI methylation for APC, HIC1 and RASSF1 in the breast carcinoma cell line MCF-7_wt and for APC and HIC1 in the doxorubicin sensitive cell line OVCAR-5." (PMID 20544021, 2010). "Expression of more than 40 genes was found to be lost in breast cancer because of promoter hypermethylation, including RASSF1A, RARβ2, HIC-1 genes." (PMID 16641902, 2006). "When HIC1 expression is restored in breast cancer, elevated levels of LCN2 are antagonized by HIC1." (PMID 40109857, 2025). "Hypermethylated in Cancer 1 (HIC1) is a tumor suppressor gene found to be subjected to epigenetic silencing in several cancer types, including prostate, liver, colorectal, lung, and breast cancer." (PMID 38473804, 2024). "Treatment of HIC1 with small interference was able to downregulate the expression of ADRB2, thereby reducing the migration and invasion of MDA-MB-231 cells which are highly malignant breast cancer cells." (PMID 37128280, 2023). "And there was a co-expression relationship between AC108474.1 and 5 ferroptosis-related genes (TAZ, ISCU, CAV1, PLIN4, and HIC1), including 1 ferroptosis driver, 2 ferroptosis suppressor and 2 ferroptosis marker, and AC108474.1 was a protective factor for breast cancer patients too." (PMID 34164433, 2021). "When we stimulated the breast cancer cell line SK-BR-3 with rhIL-8 and rhCXCL1, HIC1 expression was not decreased (data not shown)." (PMID 31795965, 2019). "Mechanistic studies showed that miR-128 could directly bind the HIC1 3’-UTR and suppress its expression, promote proliferation and invasion, and inhibit apoptosis of breast cancer cells." (PMID 31680974, 2019). "Another possible mechanism may involve the deacetylase, such as HDAC4, which has been considered as an E3 of SUMOylation of several proteins in breast cancer progression, such as silent information regulator 1 (SIRT1), IκBα, androgen receptor, and hypermethylated in cancer 1 (HIC1)." (PMID 39127633, 2024).
breast carcinoma (continued). "Using a demethylating drug 5-aza-2′-deoxycytidine (DeoxyC), HIC-1 expression was restored in the MDAMB231 cells, also suggesting restoration of HIC-1 function by reversing HIC-1 hypermethylation may offer a therapeutic avenue in breast cancer." (PMID 11747329, 2001). "However, the mechanisms regulating HIC-1 have not been reported, particularly with regard to how miRNAs regulate HIC-1 in breast cancer cells." (PMID 30202238, 2018).
prostate carcinoma (14 papers, 2011 to 2025). A carcinoma that arises from epithelial cells of the prostate gland. "Hypermethylation of HIC1 promoter results in the loss of its repressive function, and it is also a core gene mutation in prostate cancer." (PMID 31088536, 2019). "It was reported that the loss of suppressive function of HIC1 by promoter hypermethylation was responsible for prostate cancer progression and invasion." (PMID 26510908, 2015). "Thus, our results are in contradiction with previous reports using another HIC1 antibody in human prostate tumors or in a murine prostate cancer model with conditional knock-out alleles of Pten and/or Hic1 in prostate." (PMID 33227080, 2020). "Firstly, the downregulated expression of HIC1 can serve as a biomarker for prostate cancer, enhancing the early detection rate of the disease." (PMID 41050263, 2025). "This study employed high‐throughput transcriptome sequencing analysis to identify a decrease in the expression of the tumor suppressor HIC1 in prostate cancer cells." (PMID 41050263, 2025). "Subsequently, we evaluated the effects of HIC1 on the proliferation, migration, invasion, and colony formation of prostate cancer cells using CCK‐8, EdU, invasion experiments, and colony formation assays." (PMID 41050263, 2025). "In conclusion, HIC1 plays a critical role in suppressing the proliferation, metastasis, and castration resistance of prostate cancer cells in an in situ mouse model." (PMID 41050263, 2025). "To examine the impact of HIC1/AR/IRS2 on the progression of castration‐resistant prostate cancer, we injected HIC1‐silenced cells (LNCaP‐sh‐HIC1) and a control group (LNCaP‐sh‐NC) labeled with fluorescence into the posterior lobe of the prostate." (PMID 41050263, 2025). "Our study utilized high‐throughput transcriptome sequencing analysis to comprehensively elucidate the role of HIC1, a novel tumor suppressor, in the pathogenesis of prostate cancer." (PMID 41050263, 2025). "This study aims to explore the role of HIC1 in prostate cancer and investigate its potential mechanisms through high‐throughput transcriptome sequencing analysis and cell biology experiments." (PMID 41050263, 2025). "HIC1 inhibits AR expression to suppress the development of castration‐resistant prostate cancer through the IRS2/PI3K/AKT axis." (PMID 41050263, 2025). "Our findings revealed that HIC1 suppression enhanced the growth, proliferation, and invasiveness of prostate cancer cells, while upregulation of HIC1 inhibited these characteristics." (PMID 41050263, 2025). "Conversely, overexpression of HIC1 produced the opposite effect, providing further evidence of HIC1's influence on the invasive characteristics of prostate cancer cells." (PMID 41050263, 2025). "In summary, our results indicate that overexpression of HIC1 decreases AR expression, leading to reduced growth, proliferation, and metastatic potential of prostate cancer cells." (PMID 41050263, 2025). "To investigate the regulatory role of HIC1 on AR, we initially assessed the expression of HIC1 and AR in human and murine prostate cancer cell lines (including VCaP, PC3, DU145, LNCaP, and RM‐1 cells)." (PMID 41050263, 2025). "We created a mouse model of prostate cancer and observed that silencing HIC1 increased the expression levels of Ki‐67, Cleaved‐caspase‐3, and EMT‐related proteins in prostate cancer cells." (PMID 41050263, 2025). "These in vivo experiments further strengthen the evidence supporting the role of HIC1 in prostate cancer progression." (PMID 41050263, 2025). "This study sheds light on the involvement of HIC1 in prostate cancer and proposes that the regulation of the AR/IRS2 axis represents a potential mechanism through which HIC1 impacts the development of prostate cancer." (PMID 41050263, 2025). "To assess the effects of HIC1 on prostate cancer cells, we performed lentivirus infection to induce knockdown and overexpression of HIC1 in LNCaP and VCaP cells." (PMID 41050263, 2025).
prostate carcinoma (continued). "Our research findings indicate that the overexpression of HIC1 plays a crucial role in reducing castration resistance in prostate cancer cells." (PMID 41050263, 2025). "However, the exact role of HIC1 in prostate cancer and its underlying mechanisms remain unclear." (PMID 41050263, 2025). "Our constructed cell models, wherein HIC1 was either overexpressed or silenced, clearly demonstrated the crucial role of HIC1 in controlling the proliferation and invasion of prostate cancer cells." (PMID 41050263, 2025). "Lastly, we plan to conduct clinical trials to assess the effectiveness and safety of a new treatment approach targeting HIC1, offering improved treatment alternatives for patients with prostate cancer." (PMID 41050263, 2025). "The outcomes of the experiments conducted on prostate cancer cells demonstrate the influence of HIC1 expression on cell growth, proliferation, invasion, and stemness, aligning with its role in other types of cancer." (PMID 41050263, 2025). "For instance, the abundant methylation status of 11 CpG sites within the HIC1 promoter has been detected in cell lines, tissues, and plasma of patients with prostate cancer compared with normal controls." (PMID 37388742, 2023). "In prostate cancer cells, HIC1 directly represses the expression of SLUG, an EMT-inducing transcription factor." (PMID 33227080, 2020). "In a second experiment, we included these 10 tumors in a larger cohort with 20 prostate cancer samples and we measured HIC1 expression levels by RT-qPCR using the normal prostate of a young (24-year old) healthy donor as control." (PMID 33227080, 2020). "These authors thus concluded that impairment of HIC1 expression in prostate cancer cells induces their migration and metastasis by promoting EMT at two levels through increased expression of the transcription factor SLUG and of the CXCR4 receptor." (PMID 33227080, 2020). "Moreover, we aim to examine the viability of HIC1 as a biomarker by conducting extensive clinical trials to enhance early detection rates for prostate cancer." (PMID 41050263, 2025). "Restoration of HIC1 expression could suppress the proliferation, migration, and invasion and induce the apoptosis of prostate cancer cells." (PMID 37388742, 2023). "Finally, we found that TGF-β expression level was inversely correlated with HIC1 in the cell lines commonly used in prostate cancer research (R2 = 0.421), especially in the three malignant cell lines, including C4-2B, PC3, and DU145." (PMID 35853880, 2022). "Interestingly, CXCR4, the bona fide CXCL12 receptor and CXCR7, a scavenger receptor overexpressed in prostate cancers, have been both identified as direct target genes of HIC1." (PMID 33227080, 2020). "Indeed, prostate cancer incidence increases with age and HIC1 is epigenetically silenced in normal prostate aging." (PMID 33227080, 2020). "Loss of HIC1 has been associated with prostate cancer and induction of EMT, while HIC1 recently identified a group of mesenchymal progenitors in the developing limb, suggesting that HIC1 may drive a mesenchymal phenotype rather than inhibit one in certain cell types." (PMID 40736379, 2025). "This study reveals that HIC1 inhibits the progression of prostate cancer by regulating the AR/IRS2 axis, thus addressing a research gap and enhancing our understanding of HIC1's mechanism of action." (PMID 41050263, 2025). "In prostate carcinoma, a high frequency of alterations in the promoter methylation status of HIC1, SFRP2, and DAPK1 was detected in patients with prostate carcinomas of high Gleason Score (GS)." (PMID 37388742, 2023). "Moreover, the inhibitory effects of HIC1 on PCa cell proliferation and invasion, along with its potential to decrease castration resistance, suggest that HIC1 could be a promising therapeutic target for prostate cancer, opening up new avenues for clinical treatment." (PMID 41050263, 2025).
prostate carcinoma (continued). "We first determined HIC1 expression levels in 10 pairs of prostate cancer tissues and matched adjacent non-cancerous tissues." (PMID 33227080, 2020). "It was recently shown that hypermethylated in cancer 1 (HIC1), which is a tumor suppressor gene located at 17p13.3, resides exclusively within CpG islands, frequently showing hypermethylation in several tumors such as breast, lung and prostate carcinomas." (PMID 31067787, 2019). "In addition, hypermethylation of the HIC1 exacerbated prostate cancer metastasis by inducing epithelial-mesenchymal transition (EMT) mediated by Slug and CXCR4, which contributed to the poor prognosis of prostate cancer patients." (PMID 37388742, 2023).
lung carcinoma (12 papers, 2012 to 2025). "Recent research has also identified shared DNA methylation changes in vapers and smokers, including epigenetic alterations in tumor suppressor genes such as HIC1, which are linked to lung cancer development." (PMID 41568369, 2025). "HIC1 resides completely within a CpG island that is frequently hypermethylated in human tumors, including breast, prostate, and lung cancer." (PMID 35501800, 2022). "Through data mining, they also found evidence for increased expression of HIC1 in primary lung cancer cells co-cultured with CAFs as well as for an increased expression of HIC1 in non-small cell lung cancer cells treated with TGF-β." (PMID 33227080, 2020). "Furthermore, Hyper-methylated In Cancer 1 (HIC1) in cancers can not only predict the prognosis (including lung cancer) but also predict the effects of immunotherapy and drug sensitivity, marking HIC1 as a potential biomarker with immune activity." (PMID 38515565, 2024). "HIC1 is a tumor suppressor gene located at 17p13.3, which resides completely within a CpG island that is frequently hypermethylated in human tumors, including medulloblastoma, prostate, and lung cancer." (PMID 35853880, 2022).
pancreatic cancer (10 papers, 2013 to 2025). "HIC1 expression was reduced in pancreatic cancer cell lines and in tumor tissues of pancreatic cancer patients compared with non-transformed cells." (PMID 29914167, 2018). "Recent studies indicate that HIC1 methylation causes abnormal overexpression of SIRT, which contributes to the development and progression of breast, lung, and pancreatic cancers." (PMID 27793057, 2016). "In a pancreatic cancer model, restoration of HIC1 function can be accomplished by forced suppression by demethylation of the promoter and prevents cancer cell formation and reduces the aggressiveness of the tumors." (PMID 27793057, 2016). "More recently, Hu and colleagues confirmed HIC1’s repressor activity on STAT3 in pancreatic cancer." (PMID 29914167, 2018). "Previous studies indicated that overexpression of HIC1 can act as a poor prognostic biomarker for KIRC, while a biomarker for better prognosis in pancreatic cancer." (PMID 37388742, 2023). "Notably, inhibition of HIC1-mediated STAT3–DNA binding affected invasion and metastasis of pancreatic cancer cells both in vitro and in vivo." (PMID 29914167, 2018). "negative HIC1 expression predicted poor dignosis; inhibited the invasion and metastasis of pancreatic cancer cells both in vitro and in vivo; repressed the expression of STAT3 target genes, including c-Myc, VEGF, CyclinD1, MMP2 and MMP9." (PMID 29254283, 2017). "Cell-free DNA hypermethylation of BMP3, MESTv2, SST, TFPI2, TAC1, ALX4, HIC1, SFRP2, SEPT9v2 and WNT5A has not previously been described in the literature in relation to pancreatic cancer." (PMID 27891190, 2016).
colon carcinoma (9 papers, 2011 to 2025). "The epigenetic silence of HIC1 through promoter hypermethylation maintain or promote a malignant phenotype in colon tumors in a lineage-specific manner." (PMID 34642302, 2021). "The epigenetic silencing of the HIC1 gene has been frequently observed in different types of human malignancies, including gastric and liver cancers, esophageal cancers, and colon cancers." (PMID 34642302, 2021). "Firstly, analyses of 30 prostate tumors strongly suggested that HIC1 expression is correlated with tumor stroma content, as previously shown for colon carcinomas." (PMID 33227080, 2020). "In colon cancer, luteolin combined with erastin targets the tumor suppressor hypermethylated in cancer 1 (HIC1) gene, which inhibits GPX4 expression, thereby inducing ferroptosis; however, HIC1 regulation underlying ferroptosis remains unclear." (PMID 39584140, 2024). "HIC1 is also detected in the stroma of both high- and low-HIC1 expressing colon carcinomas (CRCs) and in the epithelial cancer cells of high-HIC1 CRCs which principally belong to the CMS4 subtype characterized by the worst survival and a strong stromal gene signature." (PMID 33227080, 2020).
liver cancer (9 papers, 2018 to 2025). An epithelial or non-epithelial malignant neoplasm that arises from the liver. "Hepatocyte nuclear factor 4 alpha (HNF4A) and HIC ZBTB transcriptional repressor 1 (HIC ZBTB transcriptional repressor 1) in liver cancer HIC1) binds competitively to KAT2B, inhibiting the production of GSH and promoting ferroptosis." (PMID 40327848, 2025). "have reported that HIC1 expression was negatively related to the clinical stage in patients with liver cancer." (PMID 37388742, 2023). "HNF4α has been identified as suppressing ferroptosis, and HIC1 identified as stimulating ferroptosis in liver cancer." (PMID 36105219, 2022). "Increasing the concentration of GSH by targeting HNF4α and HIC1 might improve soferanib resistance for liver cancer treatment." (PMID 36105219, 2022). "HIC1 and RassF1A methylation states were examined in 96 liver cancer sample pairs." (PMID 30249017, 2018). "We next determined whether abnormal HIC1 and RassF1A methylation and the corresponding downregulation in tubulin expression occurred in human liver cancer." (PMID 30249017, 2018). "Finally, abnormal HIC1 and RassF1A methylation was present in 96 liver cancer samples." (PMID 30249017, 2018). "It has been found that HIC1 controlled several pro-ferroptosis genes transcriptionally, such as HBA1, and promotes ferroptosis in liver cancer." (PMID 37388742, 2023). "HIC1 acts as a tumor suppressor inhibiting cell growth, migration, and survival; on the other hand, HNF4A is critical for liver development and is upregulated in liver cancer." (PMID 37132605, 2024). "The imbalance between the transcription factors HIC1 and HNF4A, regulating ferroptosis up-regulated factors (FUF), and ferroptosis down-regulated factors (FDF), respectively, may help treat liver cancer." (PMID 35047016, 2021). "However, a previous research considered HIC1 was a ferroptosis driver gene for HIC1 stimulated ferroptosis through regulating GSH synthesis, and subsequently leading to inhibition of tumor growth in liver cancer." (PMID 35071242, 2021).